TTK (TTK protein kinase)
Diseases named in the same sentence as TTK in open-access papers (continued):
Sharing a sentence is not in itself a finding about the gene and the disease.
glioma (12 papers, 2011 to 2024). A benign or malignant brain and spinal cord tumor that arises from glial cells (astrocytes, oligodendrocytes, ependymal cells). "TTK was identified as the most up-regulated gene encoding protein kinase in glioma stem-like cells." (PMID 37644431, 2023). "TTK has also been implicated in mediating the radiosensitivity of glioma cells." (PMID 35850753, 2022). "Recent research has shown that high TTK mRNA level correlates with earlier development of clinical symptoms, increased tumor aggressiveness, and poor outcome in patients with glioma." (PMID 35850753, 2022). "The up-regulated TTK promotes proliferation and clonogenicity of glioma stem-like cells (GSCs) in vitro and in vivo." (PMID 35850753, 2022). "In glioblastoma, MTFR2 can transcriptionally regulate TTK expression in maintaining glioma stem-like cells." (PMID 35600359, 2022). "RNA levels of eight major mitotic spindle assembly checkpoint (SAC) genes (BUB1, BUB1B, BUB3, CENPE, MAD1L1, MAD2L1, CDC20, TTK) significantly correlated with glioma grade and six also significantly correlated with survival time." (PMID 22022424, 2011). "Expression of six SAC genes, BUB1, BUB1B, CDC20, CENPE, MAD1L1 and TTK were found to be significantly positively correlated with WHO grades of glioma patients (p<0.01)." (PMID 22022424, 2011). "In conclusion, two SAC genes, BUB1 and TTK, showed increased RNA expression compared to normal brain even in the lowest grades of glioma, perhaps indicating their future utility for differentiating among low grade gliomas." (PMID 22022424, 2011). "Nevertheless, antibody stains for proteinsBUB1, BUB1B, BUB3, CDC20, and TTK were at significantly higher levels in high grade glioma than in normal brain by this test." (PMID 22022424, 2011). "BUB1 and TTK were significantly differentially expressed between low grade gliomas and normal brain tissues (p<0.01)." (PMID 22022424, 2011). "Besides, it has been unearthed that HLF-mediated downregulation of miR-132 leads to TTK overexpression, which contribute to proliferation, and metastasis in glioma cancerous cells." (PMID 38711550, 2024). "TTK acts as an oncogene and contributes to the radioresistance of glioma cells." (PMID 35850753, 2022). "However, TTK is commonly expressed in a variety of tumor tissues, including glioma, making it a potential target for cancer therapies." (PMID 35850753, 2022). "Another study showed that MTFR2 could regulate tumor genesis, drug resistance, and tumor recurrence in glioma by activating TTK signaling." (PMID 35600359, 2022). "MTFR2-dependent TTK regulation played a key role in maintaining GSC (Glioma stem-like cells) in glioma, and may be a target molecule of new drugs for glioma patients." (PMID 34039308, 2021). "TTK reportedly plays a role in promoting the growth of gliomas." (PMID 34631884, 2021). "Indeed, silencing TTK can inhibit the proliferation, invasion, and radiation resistance of glioma cells and other malignant behaviors." (PMID 34631884, 2021). "MTFR2 was also identified as an activator of TTK promoter in glioma stem-like cells." (PMID 33718103, 2020). "Interestingly, Ki-67 RNA level was outperformed by BUB1B and CDC20, overall, and by BUB1 and TTK when applied to grade II gliomas." (PMID 22022424, 2011). "Next, we tried to investigate whether TTK inhibitors could enhance TMZ sensitivity in glioma cells." (PMID 35850753, 2022). "Through gene correlation analysis, we identified genes positively correlated with CKAP2L, including BUB1, TTK, and ASPM, which can promote the development of glioma and treatment resistance." (PMID 34631884, 2021). "In glioma stem-like cells (GSCs), the MTFR2-dependent regulation of TTK was validated for a crucial role in maintaining GSCs in gliomas." (PMID 32121037, 2020).
liver cancer (12 papers, 2015 to 2025). An epithelial or non-epithelial malignant neoplasm that arises from the liver. "The mRNA expression of 4 hub genes, includingCDK1, HMMR, PTTG1, and TTK, were significantly associated with the survival probability of liver cancer patients in TCGA." (PMID 34187556, 2021). "These experimental data correlate well with clinical features of liver cancer patients, i.e. patients with low intratumoral TTK levels appear to have a better prognosis, associated with a much less aggressive clinical course." (PMID 27618777, 2016). "In liver cancer, the TTK inhibitor AZ3146 can enhance DNA damage, increasing the sensitivity of cancer cells to radiation." (PMID 38195567, 2024). "Inhibition of TTK alters cell-cycle progression and exacerbates centrosome abnormalities, thus promoting the radiosensitivity of liver cancer cells in a p21-mediated manner." (PMID 35850753, 2022). "The correlation between the mRNA expression of CDK1, HMMR, PTTG1, TTK, and infiltrating immune cells in liver cancer was analyzed by using the TIMER database." (PMID 34187556, 2021). "Based on the protein expression data from the HPA, the protein expression levels of CDK1, HMMR, PTTG1, and TTK in liver cancer tissues and normal liver tissues were compared by utilizing the antibodiesCAB003799, CAB002433, HPA008890, and CAB013229." (PMID 34187556, 2021). "This study also tested the utility of TTK-targeted inhibition and demonstrated its therapeutic potential in an experimental model of liver cancer in vivo." (PMID 33402113, 2021). "Four of these hub genes, including CDK1, HMMR, PTTG1, and TTK, were filtered out as potential biomarkers for diagnosis and prognosis of liver cancer." (PMID 34187556, 2021). "The dual-specificity protein kinase (TTK), a prognostic biomarker in liver cancer patients, is controlled by the mitotic spindle assembly control point and cell cycle program." (PMID 34072728, 2021). "The correlation between CDK1, HMMR, PTTG1, and TTK and gene markers for different subsets of immune cells in liver cancer were analyzed through the TIMER-related modules." (PMID 34187556, 2021). "The immunohistochemistry results confirmed that the protein expression levels of CDK1, HMMR, PTTG1, and TTK were higher in liver cancer tissues than normal liver tissues." (PMID 34187556, 2021). "Elevated expression levels of TTK in neoplastic tissues in a cohort of liver cancer patients were observed compared to neighboring healthy liver tissues." (PMID 34072728, 2021). "The mRNA levels and protein levels of CDK1, HMMR, PTTG1, and TTK were higher in liver cancer tissues compared to normal tissues, which showed excellent diagnostic and prognostic value." (PMID 34187556, 2021). "In the current study, we further validate our previous findings using another independent patient cohort, and more importantly, demonstrate a critical role of TTK in liver cancer development and progression." (PMID 27618777, 2016). "Herein, we show that levels of TTK protein are significantly elevated in neoplastic tissues from a cohort of liver cancer patients, when compared with adjacent hepatic tissues." (PMID 27618777, 2016). "In order to evaluate the therapeutic potential of TTK against liver cancer, we first examined the impact of in vitro gene silencing of TTK on cellular function of liver cancer cells." (PMID 27618777, 2016). "Specifically, in our intrahepatic xenograft mouse studies, we show that both in vitro and in vivo knockdown of TTK efficiently slow tumor growth and decrease aggressiveness of liver cancer cells." (PMID 27618777, 2016). "Determination of correlations between markedly elevated circulating TTK levels and intratumoral expression in liver cancer as well as better definition of the role in tumor biology would be the next logical steps in drug development." (PMID 27618777, 2016).
liver cancer (continued). "These proposed treatment modalities are innovative, appear specific, non-toxic and seem potentially more effective to prevent and manage progression, recurrence and death of liver cancer, and, potentially, other types of cancer that express high TTK levels." (PMID 27618777, 2016). "Following lentiviral shRNA knockdown in several human liver cancer cell lines, we demonstrated that TTK boosts cell growth and promotes cell spreading; as well as protects against senescence and decreases autophagy." (PMID 27618777, 2016). "Taken together, these data demonstrate that targeted inhibition of TTK specifically limits liver cancer cell growth promoting greater levels of senescent and autophagic cell death." (PMID 27618777, 2016). "We investigated the functional consequences of TTK inhibition on liver cancer cell death, inclusive of apoptosis, senescence and autophagy." (PMID 27618777, 2016). "Our preliminary RNA ISH results confirmed the predominant tumor-specific expression of TTK observed in a large cohort of liver cancer patients." (PMID 27618777, 2016). "We also tested the utility of TTK targeted inhibition and have demonstrated therapeutic potential in an experimental model of liver cancer in vivo." (PMID 27618777, 2016). "Following multi-omics analysis (including whole genome and transcriptome sequencing), we were able to identify the dual-specific protein kinase TTK as a putative new prognostic biomarker for liver cancer." (PMID 27618777, 2016). "Our work identifies molecular underpinnings by which TTK drives hepatocarcinogenesis, at least in part, through preventing senescent and autophagic cell death and facilitating spread of liver cancer cells." (PMID 27618777, 2016). "It demonstrats that epigenetic mechanism at least partly, induces TTK overexpression in liver cancer." (PMID 26418879, 2015). "Furthermore, the relationship between SCNA of the CDK1, HMMR, PTTG1, and TTK and infiltrating immune cells in liver cancer was explored via using TIMER." (PMID 34187556, 2021). "The CDK1, HMMR, PTTG1, and TTK were hub genes in liver cancer; hence, they might be potential biomarkers for diagnosis, prognosis, and targeted therapy of liver cancer." (PMID 34187556, 2021). "Through the DGIdb, 69 drugs interacted with CDK1, HMMR, and TTK, which might help develop new treatment target for liver cancer therapy." (PMID 34187556, 2021). "However, the exact molecular mechanisms impacted by TTK that dictate the malignant potential of liver cancer cells remain to be determined." (PMID 27618777, 2016). "Therefore, cancer vaccination using TTK peptide provides yet another potential therapeutic approach against liver cancer and other cancers." (PMID 27618777, 2016). "Taken together, our data suggest that targeted TTK inhibition might have clinical utility as an adjunct therapy in management of liver cancer." (PMID 27618777, 2016). "Furthermore, we note that, in vivo silencing of TTK, by systemically delivering TTK siRNAs to already tumor-bearing liver, limits intrahepatic spread of liver cancer cells." (PMID 27618777, 2016). "Further studies showed KIAA0101 and TTK, two reported dysregulated mRNAs in HCC, was inversely correlated with lncRNA-SVUGP2, in both liver cancer cell lines and tumor tissue." (PMID 29228655, 2017). "The TTK protein levels differ in human liver cancer between liver cancer cells and adjacent noncancerous liver cells." (PMID 33402113, 2021). "The tumor specificity of TTK expression is also supported by our data showing total or near absence of TTK in non-neoplastic liver in all liver cancer patients." (PMID 27618777, 2016). "We propose future studies to investigate the impact of TTK expression on overall survival and response to TACE and RFA in non-resectable liver cancer." (PMID 27618777, 2016). "The effect of TTK expression on the outcome of liver-directed treatment option such as TACE and radiofrequency ablation (RFA) in patients with non-resectable liver cancer remains unclear." (PMID 27618777, 2016).
bladder cancer (9 papers, 2014 to 2025). "Another study found that miR-582-5p inhibits the occurrence and development of bladder cancer by inhibiting the expression of TTK." (PMID 37072750, 2023). "TTK has been implicated in the activation of EMT in breast and bladder cancers." (PMID 36829176, 2023). "TTK can help bladder cancer cells activity and mediate epithelial-mesenchymal transition." (PMID 36849137, 2023).
endometrial cancer (9 papers, 2020 to 2025). Primary or metastatic malignant neoplasm involving the endometrium (mucous membrane that lines the endometrial cavity). "Our results demonstrated an association between high TTK and worse survival in patients with endometrial cancer." (PMID 38195567, 2024). "Additionally, Kaplan‒Meier analysis revealed that increased TTK mRNA expression was associated with a poorer prognosis, positioning TTK as a prospective biomarker for poor prognosis in patients with endometrial cancer." (PMID 38195567, 2024). "Additionally, we explored the diagnostic and prognostic value of TTK in endometrial cancer as well as its correlation with immune infiltration." (PMID 38195567, 2024). "The clinicopathological features and ROC curve analysis of TTK expression demonstrated significant associations between TTK mRNA expression and both tumor metastasis and high TNM staging of endometrial cancer patients." (PMID 40723362, 2025). "Taken together, we conclude that TTK can indeed serve as a biomarker for predicting poor prognosis in patients with endometrial cancer." (PMID 38195567, 2024). "The heightened expression of TTK in endometrial cancer was validated through multiple databases and cell lines." (PMID 38195567, 2024). "In summary, our study revealed that upregulated TTK mRNA and protein expression in endometrial cancer was positively correlated with metastasis and advanced TNM stage." (PMID 38195567, 2024). "The relationship between TTK mRNA expression and the clinicopathological characteristics of endometrial cancer patients was assessed using the Mann‒Whitney U test and logistic regression analysis." (PMID 38195567, 2024). "Our results indicate that TTK holds substantial promise as a discerning biomarker for distinguishing endometrial cancer tissue from normal tissue." (PMID 38195567, 2024). "The exact prognostic importance of TTK in endometrial cancer, as well as its connection to immune infiltration, remains incompletely understood." (PMID 38195567, 2024). "To investigate the role of TTK in endometrial cancer, we examined TTK protein and mRNA levels in endometrial cancer cell lines." (PMID 38195567, 2024). "TTK protein expression was significantly greater in endometrial carcinoma tissues than in normal tissues." (PMID 38195567, 2024). "In this study, we mined the proteomic grade correlations, and we identified protein kinases—including MAP3K2, MASTL, and TTK—that by experiment had a functional impact in vitro in uterine endometrial cancer cells." (PMID 37141409, 2023). "The potency of this TTK inhibitor suggests that targeting TTK is biologically relevant in uterine cancer cells and provides rationale for further testing in patient-derived organoid systems or animal models of endometrial cancer." (PMID 37141409, 2023). "To investigate and evaluate our hypothesis, we conducted a comprehensive assessment of the prognostic importance of TTK in endometrial cancer using The Cancer Genome Atlas (TCGA) dataset." (PMID 38195567, 2024). "TTK expression in endometrial cancer was examined by analyzing TTK expression data from the TCGA." (PMID 38195567, 2024). "Our findings also suggest a unique role for TTK in immune infiltration in endometrial cancer." (PMID 38195567, 2024). "The associations between TTK and tumor metastasis and high TNM stage suggest that TTK may be a poor prognostic biomarker in endometrial cancer." (PMID 38195567, 2024). "In our study, we detected upregulated TTK expression in endometrial cancer." (PMID 38195567, 2024). "However, the prognostic importance of TTK and its correlation with immune infiltration in endometrial cancer (EC) remain unclear." (PMID 38195567, 2024). "Immunohistochemistry revealed ISH scores for four risk kinases (ALPK2, TTK, PTK6, and CIT) were significantly higher in endometrial carcinoma tissues than in healthy endometrium, which suggested that high expression of these genes may contribute to the progression of UCEC." (PMID 36158685, 2022).
endometrial cancer (continued). "Given the well-documented overexpression of TTK in cancer and its ability to inhibit tumor cell migration upon TTK depletion, we developed a hypothesis suggesting a plausible correlation between TTK expression and survival outcomes in patients with endometrial cancer." (PMID 38195567, 2024). "We examined the correlation between TTK mRNA expression and OS and recurrence-free survival (RFS) in endometrial cancer patients using Kaplan‒Meier analysis." (PMID 38195567, 2024). "The positive correlation between TTK upregulation or metastasis and advanced TNM stage suggested that TTK is involved in endometrial cancer progression." (PMID 38195567, 2024). "Using univariate Cox regression and Least absolute shrinkage and selection operator (LASSO), seven kinases (ALPK2, CAMKV, TTK, PTK6, MAST1, CIT, and FAM198B) were identified to establish a prognostic model of endometrial cancer." (PMID 36158685, 2022). "However, the expression and prognostic value of TTK in endometrial cancer have not been extensively explored." (PMID 38195567, 2024).
lung adenocarcinoma (9 papers, 2008 to 2026). A carcinoma that arises from the lung and is characterized by the presence of malignant glandular epithelial cells. "Our study explored the prognosis of lung adenocarcinoma (LUAD) patients with different TTK levels and the possible pathological mechanism of TTK in LUAD." (PMID 35784389, 2022). "NEK2 (p<0.001) and TTK (p = 0.002) expression in the noninvolved lung tissue was also associated with a 3-fold increased risk of mortality from lung adenocarcinoma in smokers." (PMID 18297132, 2008). "In addition, there are some genes in other modules that can have very important roles in lung adenocarcinoma, namely DLGAP5, BIRC5, PSMD2, Src, TTK, SENP2, PSMD2, DOK2, FUS among others." (PMID 23874428, 2013).
melanoma (9 papers, 2015 to 2025). A malignant, usually aggressive tumor composed of atypical, neoplastic melanocytes. "In melanoma cells, TTK activates Akt and forms an auto-regulatory negative feedback loop with B-RafWT/ERK signaling." (PMID 26418879, 2015). "However, an auto-regulatory negative feedback loop between TTK and B-RafWT/ERK signaling was found in melanoma cells." (PMID 27833085, 2016).
esophageal squamous cell carcinoma (8 papers, 2012 to 2025). Esophageal squamous cell carcinoma (ESCC) is a type of esophageal carcinoma (EC) that can affect any part of the esophagus, but is usually located in the upper or middle third. "A phase I trial for advanced esophageal squamous cell carcinoma in patients with HLA-A*2402 demonstrated that a combination of LY6K and TTK with CpG-7909 elicited potent LY6K-specific T cell responses." (PMID 39727968, 2024).